NDRG4 (NDRG family member 4)
Diseases named in the same sentence as NDRG4 in open-access papers (continued):
Sharing a sentence is not in itself a finding about the gene and the disease.
colorectal cancer (continued). "However, we found that NDRG2 and NDRG4 mRNA expression was both decreased in colorectal cancer and adversely associated with clinical outcome within the same study cohort, indicating a tumor suppressive role of NDRG4 in colorectal cancer, which was similar to the role of NDRG2 in colorectal cancer." (PMID 26515606, 2016). "Similarly, NDRG4, known to influence PI3K/AKT and MAPK/ERK signaling, plays important roles in cell cycle regulation and the inhibition of apoptosis in breast and colorectal cancers." (PMID 40503897, 2025). "It has been demonstrated that NDRG4 plays a role as a tumor suppressor via inhibiting the PI3K/AKT signaling in colorectal cancer cells, and it can act as a prognostic predictor for patients with colorectal cancer." (PMID 40378957, 2025). "The DNA methylation biomarkers BMP3 (bone morphogenetic protein 3), NDRG4 (N-myc downstream-regulated gene 4) and SDC2 (syndecan-2) has been extensively studied and are served as an alternative method in screening colorectal cancers and neoplasms 5, 16, 31, 35-44." (PMID 33391430, 2021). "Moreover, integration of SEPT9, NDRG4, and SDC2 methylation demonstrated high feasibility for detecting colorectal cancer and adenoma, with better performance on colorectal cancer than adenoma." (PMID 31602277, 2019). "Significantly increased NDRG4 promoter methylation levels were observed in colorectal cancer tissues compared to paired non-tumor tissues." (PMID 28042954, 2017). "While in NDRG4 negative staing subgroup, colorectal cancer of positive p-AKT staining had poor survival." (PMID 25749388, 2015). "In positive NDRG4 staining subgroup, patients with colorectal cancer of negative p-AKT staining had favorable survival." (PMID 25749388, 2015). "Intriguingly, colorectal cancer with both positive NDRG4 and p-AKT staining showed no prognostic difference compared with those with both negative staining of NDRG4 and p-AKT." (PMID 25749388, 2015). "Multivariate analysis showed that NDRG4 could be a prognostic factor for overall survival of patients with colorectal cancer independent of gender, age, differentiation status, TNM stage, KRAS, BRAF and PIK3CA mutations and MSI status." (PMID 26515606, 2016). "However, patients with colorectal cancer of both positive staining of NDRG4 and p-AKT was not significantly different from those with both negative staining in outcomes." (PMID 25749388, 2015). "Positive NDRG4 staining was an independent predictor of favorable survival in a cohort including 272 Chinese colorectal cancer (CRC) patients; however, we could not find the support evidence from 174 CRC patients in TCGA4U, a web-based platform using TCGA datasets (P > 0.05, data not shown)." (PMID 28042954, 2017). "Considering the role of NDRG4 in the potential link with energy balance by PI3K/AKT attenuation, we hypothesized that activation of PI3K/AKT by absent NDRG4 expression might confer proliferative and progressive ability to colorectal cancer cells under excess energy balance status." (PMID 26515606, 2016).
adenoma (10 papers, 2017 to 2025). A neoplasm arising from the epithelium. "The sensitivity and specificity of fecal DNA multi-target testing, including KRAS mutation, BMP3, and NDRG4 methylation, for CRC and advanced adenoma was 80%, 91.2%, and the corresponding area under the curve was 0.856." (PMID 36905607, 2023). "Same as mutation markers, relative methylation level of Septin9, NDRG4, and BMP3 in CRC samples were higher than adenoma and NED groups, consistently in training and validation data sets." (PMID 33718241, 2021). "N-myc downstream regulated gene 4 (NDRG4) could be also considered as a significant diagnostic marker gene in CRC (DOR: 24.37; 95%CI, 10.11–58.73) and Vimentin (VIM) in adenoma (DOR: 15.21; 95%CI, 2.72–85.10)." (PMID 30024936, 2018). "Besides, NDRG4 could be also considered as a significant diagnostic marker gene in CRC (DOR: 24.37; 95%CI, 10.11–58.73) and VIM in adenoma (DOR: 15.21; 95%CI, 2.72–85.10)." (PMID 30024936, 2018). "Besides, NDRG4 and VIM could also be considered as significant diagnostic marker genes in CRC and adenoma, respectively." (PMID 30024936, 2018). "An additional gene found to exhibit hypermethylation in stool samples from individuals with high-grade dysplasia, adenomas, and CRC is N-Myc downstream-regulated gene 4 (NDRG4), which codifies a protein involved in cell cycle regulation and differentiation." (PMID 38248446, 2023). "We further checked the performance when combining methylated SEPT9, NDRG4, and SDC2 for detecting adenoma and CRC." (PMID 31602277, 2019). "All these results indicated that the combination of SEPT9, NDRG4, and SDC2 methylation levels was sufficient for effective detection of CRC and adenoma." (PMID 31602277, 2019). "Methylation of SEPT9, NDRG4 and SDC2 combined has high feasibility for detecting CRC and adenoma, with better performance for detecting CRC over adenoma." (PMID 31602277, 2019). "One was the panel consisting of methylated BMP3/NDRG4/VIM/TFPI2/mutant KRAS, β-actin, and Hb-level (and later refined and commercialized as Cologuard®), which in stool detected CRC with 87% sensitivity, adenoma with 82% sensitivity, and demonstrated a specificity of 93%." (PMID 33030559, 2021). "Furthermore, the combination of methylated SEPT9, NDRG4, and SDC2 showed high feasibility of detection of CRC and adenoma and further study showed better performance in detecting CRC than adenoma." (PMID 31602277, 2019). "BMP3, NDRG4, and SDC2 showed a significantly higher methylation level in CRC than adenoma samples." (PMID 31602277, 2019). "One hundred and twenty colorectal samples (including 58 normal tissues, 46 adenomas, four Stage I CRC, eight Stage II CRC, and four Stage III CRC) were selected from the large sample set, and the methylation status of BMP3 and NDRG4 was determined by mass spectrometry." (PMID 29371978, 2017). "Furthermore, a 4-biomarker panel was the only one combining methylated BMP3, NDRG4, SDC2 with FOBT (and not FIT), achieving a moderately good performance for detection of CRC, 85.4% sensitivity and 92% specificity, and all adenomas (85.7% sensitivity)." (PMID 40402271, 2025).
meningioma (9 papers, 2014 to 2021). A generally slow growing tumor attached to the dura mater. "For this purpose, 44 WHO grade I meningiomas, including 8 showing regrowth after radiosurgery, were analysed for Ki-67 and NDRG4 protein expression, loss of 1p36 and promotor hypermethylation of the genes NDRG1-4, SFRP1, HOXA9 and MGMT." (PMID 34385566, 2021). "The NDRG4 isoform is preferentially expressed in brain and heart and its overexpression has been linked with an aggressive behavior of meningioma tumors." (PMID 24758227, 2014). "In contrast, NDRG4 has been shown to be overexpressed in high grade malignant meningioma cell lines." (PMID 34385566, 2021). "In fact, NDRG4 is upregulated in tumors of central nerve system, such as glioblastoma and meningioma, functioning as an oncogene." (PMID 32927604, 2020). "Using in vitro models, they showed that NDRG4-silencing induced apoptosis and reduced the invasive potential of the meningioma cell lines IOMM-Lee and CH-157 MN." (PMID 31485792, 2019). "We recently showed that N-Myc down regulated gene 4 (NDRG4) was overexpressed in aggressive meningioma." (PMID 26053091, 2015). "In summary, this is the first report demonstrating that NDRG4 silencing induces apoptotic cell death in aggressive meningioma cell lines." (PMID 26053091, 2015). "We believe that our studies evaluating the role of NDRG4 in meningioma biology are important for meeting that challenge." (PMID 26053091, 2015). "Given the increased expression levels in aggressive meningiomas, studies were best undertaken first with NDRG4 protein depletion." (PMID 26053091, 2015). "Moreover, NDRG1, NDRG2, and NDRG4 are all involved in cancers of the nervous system, such as glioma, neuroblastoma, or meningioma." (PMID 31485792, 2019). "No other (clinical) studies are available that investigate NDRG4 in the context of meningioma, so it is unclear whether NDRG4 is indeed involved in meningioma pathology in patients." (PMID 31485792, 2019). "It is clear that the understanding of NDRG4 function in the development of meningioma pathology may give new insights in future therapeutic strategies including gene therapy." (PMID 26053091, 2015). "We have recently identified NDRG4 overexpression in aggressive meningiomas." (PMID 26053091, 2015). "NDRG4 is involved in modulating cell proliferation, invasion, migration and angiogenesis in meningioma, and may play a valuable role as a molecular target in its treatment." (PMID 26053091, 2015). "Thus, it seems that NDRG4 is necessary for meningioma cells to survive." (PMID 31485792, 2019).
meningioma (continued). "Hence, selectively targeting NDRG4 with lentiviral mediated gene silencing may be a potential cancer therapy for malignant meningiomas." (PMID 26053091, 2015). "NDRG4 gene knockdown resulted in decreased expression of Bcl-2 and BcL-xL, translocation of activated BAX into the mitochondria, cytochrome c release and enhanced cleaved caspase expression in meningioma cells." (PMID 26053091, 2015). "To determine the role of NDRG4 in the molecular mechanism of apoptosis, we analyzed mitochondrial Bcl-2 family protein expression in presence or absence of NDRG4 in meningioma cell lines by western Immunoblotting, 72 hrs post infection." (PMID 26053091, 2015). "The relationship between NDRG4 and cell survival in meningioma is not established yet in vivo but knockdown of NDRG4 decreases migration, invasion and inhibited cell cycle progression in meningioma cells." (PMID 26053091, 2015). "In our previous studies, we demonstrated that NDRG4 was overexpressed in IOMM-Lee and CH-157 MN cells and NDRG4 silencing inhibited cell proliferation, motility, invasion and angiogenesis in high grade meningioma cell lines." (PMID 26053091, 2015). "However, the detailed contribution of the NDRG4 protein and its biological significance in malignant meningiomas has not been studied." (PMID 26053091, 2015). "Moreover, we could not demonstrate that NDRG4 promotor hypermethylation is the possible mechanism downregulating NDRG4 expression in low grade meningiomas." (PMID 34385566, 2021). "In our study NDRG4, highly expressed in all nontumoral brain control tissue, was not expressed in WHO I meningiomas." (PMID 34385566, 2021).
glioblastoma (7 papers, 2015 to 2024). The most malignant astrocytic tumor (WHO grade IV). "This is consistent with a previous study reporting that NDRG4 knockdown causes G1 arrest and an increase of P27 expression in glioblastoma multiforme cells." (PMID 33211401, 2021). "In terms of downregulated genes in glioblastoma, we found NDRG4, SERPINA3, RPN2, VIM, and TIMP1 to be differentially the most downregulated genes." (PMID 38769480, 2024). "Most of the recent studies reported an elevation of NDRG4 in brain tumors, where it promoted cell cycle progression and survival of glioblastoma cells." (PMID 32927604, 2020). "Knockdown of the NDRG4 gene dramatically decreases cell viability of glioblastoma cells." (PMID 29254199, 2017). "While it was found that NDRG2 and NDRG4 had opposing protein expression patterns when comparing normal brain tissue to glioblastoma tissue, suggesting the opposite function of NDRG4 to NDRG2, although NDRG4 is most similar to NDRG2 within the NDRG family." (PMID 25749388, 2015).
gastric cancer (5 papers, 2017 to 2026). A primary or metastatic malignant neoplasm involving the stomach. "More importantly, NDRG4 promoter hypermethylation was shown to be associated with poor OS of gastric cancer (HR = 1.881, 95% CI = 1.107-3.218, P = 0.020)." (PMID 28042954, 2017). "Collectively, NDRG4 promoter hypermethylation contributed to the risk of gastric cancer and predicted a poor prognosis in Chinese gastric cancer patients." (PMID 28042954, 2017). "Future recent research on the interaction of genetic polymorphisms and epigenetic marks on NDRG4 gene might be useful to elaborate the role of this gene in gastric cancer risk." (PMID 28042954, 2017). "Moreover, the combined methylation levels of NDRG4 promoter and gene body served as diagnostic biomarkers in gastric cancer." (PMID 28042954, 2017). "For one thing, DNA methylation as a biomarker was more effective in the serum than that in tissues among gastric cancer patients; therefore, NDRG4 methylation might have a higher diagnostic value in serum detection." (PMID 28042954, 2017). "Therefore, we tend to explore the association of NDRG4 with gastric cancer in Chinese." (PMID 28042954, 2017). "In current study, we extract available The Cancer Genome Atlas (TCGA) data for discovering potentially risk sites and assess the NDRG4 methylation level in gastric cancer patients to determine whether NDRG4 methylation is associated with the gastric cancer risk." (PMID 28042954, 2017). "Serum pepsinogen detection in a meta-analysis generated an AUC of 0.76, which was compatible with the AUC of 0.73 of NDRG4 promoter hypermethylation in gastric cancer tissues." (PMID 28042954, 2017). "In the present study, we reported for the first time that NDRG4 promoter hypermethylation served as a predictive biomarker in gastric cancer in spite of moderate sensitivity and specificity." (PMID 28042954, 2017). "Additionally, we explore the prognostic value of NDRG4 methylation in gastric cancer patients and integrate TCGA clinical data for validating the results that we found in Chinese population." (PMID 28042954, 2017). "NDRG2 and NDRG4 belong to one subfamily based on sequence homology; however, the role of NDRG4 methylation in gastric cancer is largely unknown." (PMID 28042954, 2017). "Screening for NDRG4 body hypermethylation might have clinical significance for the evaluation of younger patients with gastric cancer." (PMID 28042954, 2017). "Meanwhile, NDRG4 promoter hypermethylation was identified as an independent prognostic factor for survival outcomes in Chinese gastric cancer patients, and it exerted a tumor suppressive role in carcinogenesis and progression through attenuation of NDRG4 expression." (PMID 28042954, 2017). "Firstly, we measured NDRG4 promoter methylation levels in five human gastric cancer cell lines (MKN-74 from well differentiated adenocarcinoma; MKN-45, MGC-803, BGC-823 and AGS, from poorly differentiated adenocarcinoma) and non cancerous gastric mucous cell (GES-1)." (PMID 28042954, 2017). "In conclusion, our findings suggested that NDRG4 CpG island hypermethylation could be a potential biomarker for diagnosis of gastric cancer." (PMID 28042954, 2017). "In addition, those poorly differentiated tissues were inclined to accompany the NDRG4 body methylation changes during gastric cancer progression, suggesting the potential to distinguish different stages of differentiation." (PMID 28042954, 2017). "However, NDRG4 gene body methylation was not shown to be associated with gastric cancer prognosis (P = 0.504)." (PMID 28042954, 2017). "Therefore, we speculated that NDRG4 overall hypermethylation at promoter and gene body CGI could contribute to the risk of gastric cancer through its regulation of gene expression." (PMID 28042954, 2017).
colon cancer (4 papers, 2017 to 2025). "NDRG4 is involved in the regulation of cell cycle progression and has been identified as a novel tumor suppressor in colon cancer." (PMID 29285217, 2017). "BMP3 is one of two methylation markers (the other is NDRG4) included in the commercially available fecal Cologuard® test, approved by the FDA in 2014 as a colon cancer screening test." (PMID 33030559, 2021). "Cologuard©, Epi proColon©, and EarlyTect© are non-invasive screening tests for colon cancer that are currently in use and rely on the methylation of genes such as BMP3, NDRG4, SEPT9, SDC2 for early detection." (PMID 35663592, 2021). "Notably, it is significantly overexpressed in colon cancer (CLC), where its downregulation has been shown to mitigate the malignant traits of CLC cells by inhibiting the expression of NDRG4." (PMID 40462237, 2025).
glioma (4 papers, 2016 to 2022). A benign or malignant brain and spinal cord tumor that arises from glial cells (astrocytes, oligodendrocytes, ependymal cells). "One study described increased NDRG4 expression, while others report downregulation of NDRG4 in glioma." (PMID 31485792, 2019). "In contrast to NDRG2, the studies regarding expression of NDRG4 in glioma show conflicting outcomes." (PMID 31485792, 2019). "Furthermore, in the NDRG family, NDRG2 acts in a tumor-suppressive manner similar to NDRG1, while NDRG4 is lowly expressed in gliomas and is considered as a poor prognostic factor." (PMID 35448004, 2022). "In addition, reduced NDRG4 protein expression was found as a predictor for poor prognosis and reduced overall survival in both low- and high-grade gliomas (n = 128)." (PMID 31485792, 2019). "Of these 8 genes, 6 (SULT4A1, NDRG4, GAP43, BEX1, HINT1, LZTS1) are believed to act as tumor suppressants, while the remaining two, PKM and VIPR1, have been found to be overexpressed in glioma." (PMID 28957313, 2017).
Alzheimer disease (3 papers, 2019 to 2025). A progressive, neurodegenerative disease characterized by loss of function and death of nerve cells in several areas of the brain leading to loss of cognitive function such as memory and language. "The NDRG family member 4 (NDRG4) gene, highlighted in our analysis, is reportedly implicated in Alzheimer’s disease (AD)." (PMID 31779658, 2019). "On the contrary, the expression of the other two NDRG family members, NDRG3 and NDRG4, were lower in the brains of patients with Alzheimer’s disease relative to human normal adult brain." (PMID 40378957, 2025).